INS (insulin)
Diseases named in the same sentence as INS in open-access papers (continued):
Sharing a sentence is not in itself a finding about the gene and the disease.
Obesity (continued). "Lipolysis is a key metabolic function of adipose tissue that is negatively regulated by insulin signaling and is frequently impaired in individuals with obesity and T2D." (PMID 41329353, 2025). "Such adaptive changes are particularly important in the context of obesity, where lipid metabolism is often impaired due to insulin resistance, chronic inflammation, and hepatic steatosis." (PMID 41303531, 2025). "Obesity has been demonstrated to induce systemic oxidative stress and to precipitate the development of complications through mechanisms that affect the insulin signaling pathway, adipocyte function, and inflammatory response." (PMID 40687585, 2025). "The mechanisms that promote obesity‐related metabolic complications are multifactorial and include insulin resistance, adverse fat distribution, altered adipokine secretion, subclinical chronic metabolic inflammation and impaired AT dysfunction." (PMID 40069923, 2025). "A large-scale epidemiological studycompared the incidence of obesity-related cancers in patients treated with GLP1R agonists versus those treated with insulin or metformin." (PMID 39777709, 2025). "The complex crosstalk between adipokines, insulin signaling, and CNS integrity warrants further study, particularly in models that include metabolic comorbidities such as obesity or T2D." (PMID 40948809, 2025). "Exploratory stratification further suggested sex- and age-specific differences, supporting the view that insulin dysregulation can occur independently of overt obesity and requires dynamic assessment beyond visual scoring." (PMID 41302145, 2025). "GLP-1 analogues, such as liraglutide (Saxenda), are widely used to treat obesity and diabetes by regulating insulin secretion and food intake, but they have recently been found to increase the risk of acute pancreatitis." (PMID 40076460, 2025). "Systemic administration of agomir miR-293-5p in mice with diet-induced obesity ameliorated metabolic dysfunction by improving glucose disposal and insulin sensitivity." (PMID 40846699, 2025). "Obesity disrupts insulin sensitivity and promotes adipose inflammation, with exosomes playing a critical role in these processes." (PMID 40659888, 2025). "Most obesity-related compounds in the blood are also in saliva, i.e., insulin, leptin, α-amylase, tumor necrosis factor α/interleukin 6, C-reactive protein, and adiponectin." (PMID 40565251, 2025). "Overall, the findings demonstrate for the first time that MPP treats obesity by alleviating dyslipidemia, improving insulin resistance, and regulating gut microbiota to improve the intestinal environment." (PMID 40870827, 2025). "Adiponectin resistance in obesity diminishes the ability of adiponectin to maintain insulin sensitivity, blood glucose levels, and hepatic fat accumulation." (PMID 40985048, 2025). "In summary, higher activity of LAT1 and overexpression of VMAT2 in patients with obesity can temporarily enhance insulin secretion." (PMID 40099262, 2025). "TMEM18 expression is downregulated in the adipose tissue of children with obesity, correlating with impaired adipocyte formation and insulin resistance." (PMID 41082226, 2025). "Under physiological conditions, TLR4−/− mice display altered gut motility and changes in ENS neuronal composition in both the small intestine and colon, yet they are protected from obesity-induced inflammation and insulin resistance." (PMID 41226745, 2025). "Clinical trials have further demonstrated that physical activity interventions can effectively enhance insulin sensitivity in adults with overweight, obesity, or prediabetes." (PMID 41286497, 2025). "Overabundant immune infiltration and crown-like structure formation in adipose tissue are hallmarks of unhealthy adipose tissue, as observed in individuals with insulin insensitivity or obesity." (PMID 40565100, 2025).
Obesity (continued). "In individuals with obesity, 8 weeks of moderate-to-high intensity exercise (2 to 4 times/week on 65% to 85% of heart rate reserve) improved insulin sensitivity and reduced visceral adiposity." (PMID 41295278, 2025). "Here the authors show that lowering IGF-1R levels in endothelial cells improves insulin sensitivity, boosts energy use, and supports beneficial changes in adipose tissue, offering insights into potential treatments for obesity-related metabolic disorders." (PMID 39747815, 2025). "In line with this, administration of an earlier synthetic pan-ERR agonist, SLU-PP-332, reduce obesity and improve insulin sensitivity in mouse models of metabolic syndrome." (PMID 41173363, 2025). "Prolonged infant exposure to hyperglycemia and hyperinsulinemia leads to late life obesity, which can be correlated with insulin concentration in amniotic fluid." (PMID 40077697, 2025). "In the control group, T2DM participants received either placebo or other hypoglycemic agents, including metformin, insulin, and alpha‐glucosidase inhibitors, while participants with obesity received only placebo." (PMID 40887719, 2025). "In this narrative review, we describe nutraceuticals, probiotics and bioactive compounds that have been shown to have effects on obesity and their mechanisms of action, first on weight management and insulin sensitivity, and then in single comorbidities." (PMID 40431370, 2025). "PI3KγNest mice were largely protected from diet-induced obesity and liver steatosis and showed improved glucose tolerance and insulin sensitivity." (PMID 39811649, 2025). "IR induces metabolic disturbances, including obesity, elevated insulin levels, hyperglycemia, and dyslipidemia, which, in turn, trigger inflammatory responses and oxidative stress." (PMID 41419984, 2025). "Moringa peregrina (MP) leaf extracts also mitigated high-fat diet (HFD)-induced obesity in rats, reducing food intake, weight gain, fat deposition, plasma glucose, insulin, and leptin levels while improving glucose tolerance." (PMID 40149610, 2025). "In obese mice, insulin enhances MCH neuron activity, contributing to hallmark features of obesity such as reduced locomotor activity and insulin and glucose resistance." (PMID 40710295, 2025). "Pharmacological interventions were further divided into insulin sensitizers and anti-androgen drugs, anti-obesity drugs, oral contraceptive pills (OCPs), and ovulation induction drugs." (PMID 40430499, 2025). "In individuals with obesity, changes to the size, number, and cargo composition of AdEVs have been reported, with implications for insulin signaling and inflammatory pathways." (PMID 40522819, 2025). "Accordingly, peripheral insulin sensitivity (M value and M/I) measured with a euglycemic hyperinsulinemic clamp was reduced in subjects with obesity." (PMID 40666326, 2025). "Several factors, including an HFD, astrocyte activation, obesity, inflammation, diabetes, and elevated triglyceride levels, can disturb the insulin transport process and signaling receptor." (PMID 40362446, 2025). "In the present study, we demonstrated that the putative anti-obesity disaccharide trehalose reduces body weight, fat mass, hepatic lipid accumulation, and insulin insensitivity in HFD-fed mice." (PMID 40529415, 2025). "Although the mechanisms linking obesity and ineffective lipolysis within the COC are not well-established, a study on adipocytes showed decreased catecholamine-stimulated lipolysis and an antilipolytic effect of insulin in obesity." (PMID 40408431, 2025). "Excessive consumption of high-energy foods rich in fat and fructose can lead to obesity, increased visceral and epididymal fat, insulin insensitivity, hyperglycemia, and dyslipidemia, all of which are Mets." (PMID 40141836, 2025). "(v) Finally, we show that m6A levels in selected targets correlate with clinical variables of obesity, fat distribution and glucose and insulin metabolism." (PMID 41225618, 2025).
Obesity (continued). "Our analysis of NRAC expression in a human cohort of patients with obesity identified associations that indicate an adipose depot and gender specific role of NRAC in tissue expansion and regulation of systemic insulin sensitivity." (PMID 40750702, 2025). "A recent study using a different Ccdc92 KO mouse model showed that the KO mice developed reduced obesity and increased insulin sensitivity under high-fat diet conditions, indicative of a function of CCDC92 in the white adipose tissue." (PMID 41378450, 2025). "Pharmacological interventions aimed at repolarising ATMs from M1 to M2 phenotypes, or at least attenuating M1-associated inflammatory actions, are significant for improving insulin sensitivity and ameliorating obesity-related metabolic complications." (PMID 41226484, 2025). "Collectively, these findings highlight the potential of TGR5 agonism to address multiple pathophysiological features of obesity, including hyperphagia, insulin resistance, lipid accumulation, and reduced energy expenditure." (PMID 41153686, 2025). "During long-term obesity, the substantial deposition of organ and peripheral fat reduces target organ sensitivity to insulin (INS)." (PMID 39984861, 2025). "Obesity (especially high amounts of visceral fat) exerts detrimental effects of insulin sensitivity via the production and release of proinflammatory adipocytokines." (PMID 41241045, 2025). "In our research, 11.86% of the subjects presented with genetic alterations in obesity-associated genes, with 16% of these modifications involving concurrent duplications in SEZ6L2-1 and SH2B1-2, linked to doubled insulin and tripled HOMA-IR levels." (PMID 40429924, 2025). "Many molecules orchestrate the energetic metabolic processes in obesity, and insulin is one of the most prominent." (PMID 40076851, 2025). "These SCFAs have an impact on the host’s energy homeostasis, obesity, inflammation, blood glucose regulation, insulin sensitivity, and hormone secretion." (PMID 40948779, 2025). "Participants with severe obesity (BMI ≥ 40.0) showed a median insulin concentration of 92.7 μU/mL, with a wide IQR of 37.4 to 251.0 μU/mL." (PMID 40868057, 2025). "The relationship between physical activity, sedentary behavior, and obesity with cancer incidence can be explained by the interaction involving endogenous sex steroids and metabolic hormones, insulin sensitivity, and chronic inflammation." (PMID 41210336, 2025). "THC also improved adipose tissue insulin sensitivity and reduced hepatic steatosis and systemic inflammation in rodent models of obesity and MASLD." (PMID 41471280, 2025). "High insulin and low GH levels are frequently observed in obesity, with reduced energy expenditure and further fat accumulation." (PMID 40563961, 2025). "The main metabolic product of Blautia in the intestine is acetate, which, by activating the GPR41 and GPR43, inhibits insulin signaling and fat accumulation in adipocytes, thereby promoting lipid and glucose metabolism and alleviating obesity." (PMID 41376058, 2025). "Celastrol reduces M1 macrophage polarization, improves insulin sensitivity, and markedly reduces body weight in diet-induced obesity." (PMID 41463063, 2025). "MASLD represents the hepatic manifestation of metabolic syndrome and is closely connected to obesity, changes in hepatic insulin resistance, and glucose metabolism." (PMID 39826021, 2025). "Recent studies explored the use of MMP activators or small molecules to enhance ECM remodeling, demonstrating improvements in adipose tissue expandability and insulin sensitivity in animal models of obesity." (PMID 40699742, 2025). "In previous FDG‐PET studies in people with obesity and IR, increased insulin‐stimulated BGU was found to be inversely associated with whole‐body insulin sensitivity, suggesting that the BGU is oppositely regulated compared to peripheral tissues." (PMID 40926735, 2025).
Obesity (continued). "Studies have shown that Ashwagandha can modulate cortisol levels, reduce fat accumulation, and improve insulin sensitivity, making it a promising candidate for obesity management." (PMID 40508039, 2025). "Knockout of RIIβ expressed in hypothalamic GABAergic neurons can increase insulin sensitivity, enhance white adipose tissue browning, increase energy expenditure, and resist obesity induced by a high-fat diet." (PMID 40130157, 2025). "Together, we conclude that MICT1 promotes thermogenesis and enhances energy expenditure in mice and can reduce adiposity and improve insulin sensitivity in obesity." (PMID 40355556, 2025). "A marked increase in fasting glucose and insulin levels after 11 weeks of high-fat feeding was demonstrated in a study on a mouse obesity model." (PMID 40943267, 2025). "FAHFAs, which possess antiinflammatory and insulin-sensitizing properties, were lower in individuals with obesity (e.g., FAHFA 18:1/18:0 and FAHFA 16:0/22:3)." (PMID 40548377, 2025). "For example, hyperprolactinaemia promotes weight gain, obesity and metabolic syndrome by inhibiting physiological dopaminergic tone and impairing glucose–insulin and lipid metabolism." (PMID 40464046, 2025). "These saturated fatty acids alter the hypothalamic control of energy homeostasis by inducing hypothalamic inflammation and insulin and leptin resistance, thereby promoting obesity." (PMID 40690443, 2025). "Recent evidence shows EPO exerts anti-inflammatory effects in insulin-sensitive tissues, thereby improving insulin sensitivity in the context of obesity." (PMID 40697664, 2025). "On the other hand, neurological or psychological conditions, such as stress, induce the secretion of both glucocorticoids (increase motivation for food) and insulin (promotes food intake and obesity)." (PMID 39813287, 2025). "It has been shown that DNA damage can provoke inflammatory processes in visceral adipose tissue, leading to impaired lipid metabolism and systemic insulin resistance and exacerbating the course of obesity." (PMID 41465437, 2025). "Obesity-related metabolic disorders are exacerbated by excess adipose tissue infiltrating other organs, reducing insulin effectiveness." (PMID 40141412, 2025). "These cytokines are well-established in obesity-induced inflammation and have been shown to impair insulin signaling, promote endothelial activation, and contribute to adipocyte dysfunction." (PMID 40981199, 2025). "This reduction possibly reflects the detrimental effects of HFD‐induced obesity on the growth factor environment owing to insulin resistance." (PMID 40688596, 2025). "Obesity‐conditioned macrophages and T cells in adipose tissue remain in a pro‐inflammatory, insulin‐resistant state (sometimes termed ‘trained immunity’ or innate immune memory) that can reactivate quickly if weight is regained." (PMID 40684278, 2025). "Adiponectin is an insulin‐sensitizing hormone produced by adipocytes for the maintenance of metabolic homeostasis, and its levels are decreased in obesity." (PMID 40523654, 2025). "All the studies included for the calculation of an overall mean difference of FPG, FPI, HbA1c, HOMA-IR and insulin sensitivity were based on participants with overweight/obesity." (PMID 39917538, 2025). "The present study investigated the effect of regular mango intake on inflammation and insulin sensitivity in participants with overweight or obesity and chronic low-grade inflammation." (PMID 39940348, 2025). "This inhibition impairs insulin secretion, glucose uptake, and satiety regulation, ultimately contributing to the development of metabolic disorders, including obesity." (PMID 40863916, 2025). "Some research has indicated that these dietary modifications have demonstrated benefit in T2DM patients suffering from obesity, as circulating glucose decreases and insulin sensitivity increases in ketotic states." (PMID 40462791, 2025).
Obesity (continued). "Obese and diabetic participants exhibited a high insulin-resistant state in comparison with control (p < 0.001); interestingly, diabetic subjects with obesity exhibited the highest value." (PMID 40095937, 2025). "IF in rodents consistently results in improved insulin sensitivity, lower fasting glucose and insulin levels, and protection against high-fat diet-induced obesity." (PMID 41039401, 2025). "We generated fat tissue-specific adenosine A2AR KO mice to assess the influence of signaling through this receptor on brown and beige fat functionality, obesity, insulin sensitivity, inflammation, and liver function." (PMID 39828097, 2025). "The altered dynamics of leptin and insulin in obesity underscore the distinct roles of vWAT and sWAT in metabolic health." (PMID 41373779, 2025). "NEU1’s involvement in several metabolic diseases has been reviewed previously, highlighting its complex regulatory effects on insulin signaling, obesity, and non-alcoholic fatty liver disease (NAFLD)." (PMID 41301440, 2025). "Evidence associates the increased expression of TLRs, except TLR3, with inflammation and decreased insulin sensitivity in obesity-induced AT." (PMID 40076851, 2025). "Resistin, frequently elevated in obesity, promotes neuroinflammation, disrupts insulin signaling, and accelerates β-amyloid (Aβ) deposition and tau pathology." (PMID 41155642, 2025). "This dietary approach led to an average HbA1c reduction of 1.07%, along with improvements in insulin resistance, lipid profile, and obesity levels." (PMID 39852366, 2025). "Directly Altering the Structure of Gut Microbiota: Transplanting the gut microbiota from lean, healthy individuals to patients with obesity and metabolic syndrome can effectively improve the recipients' insulin sensitivity." (PMID 40027477, 2025). "Clinical studies demonstrate an inverse relationship between serum omentin-1 levels and obesity, fasting insulin, and impaired glucose tolerance." (PMID 40940776, 2025). "Obesity is known to activate the sympathetic nervous system, increase leptin resistance, elevate circulating insulin levels, and induce RAAS activity, all of which contribute to increased vascular resistance and volume overload." (PMID 41050013, 2025). "In this mouse strain, impaired leptin signalling in the hypothalamus leads to hyperphagia and obesity accompanied by elevated levels of insulin and leptin, hyperglycaemia, and the development of insulin resistance." (PMID 40149720, 2025). "For example, adipocyte-specific knockout of PKD1 improved insulin and glucose tolerance in vivo, conferred protection against obesity and T2D, and promoted the formation of beige adipocytes." (PMID 41349796, 2025). "Both groups developed metabolic dysfunction, including impaired glucose tolerance, reduced insulin sensitivity, and increased body/kidney weights, confirming successful obesity induction." (PMID 40999903, 2025). "In NAFPD mice, a 1.5 mg/kg terazosin dose markedly ameliorated obesity, hyperglycemia, and insulin sensitivity." (PMID 39413003, 2025). "This study demonstrates that RFE improves obesity-induced insulin sensitivity by regulating basal GLUT4 expression." (PMID 40076460, 2025). "APOA4 increases TG secretion and insulin production, inhibits gluconeogenesis, and is involved in obesity and type 2 diabetes pathology." (PMID 41226441, 2025). "Aerobic exercise improves insulin resistance and reduces fatigue levels, and resistance training boosts muscle mass in sarcopenic obesity, increasing activity capacity." (PMID 41141254, 2025). "The first factor, “Perceptions of Body Weight/Obesity”, highlights concerns about body image and weight, emphasizing the psychological effects of insulin-related weight gain." (PMID 40867383, 2025). "Preclinical studies suggest that postbiotics can modulate adipogenesis, improve insulin sensitivity, and reduce systemic inflammation—all key factors in the pathophysiology of obesity." (PMID 40508171, 2025).